GATA6 (GATA binding protein 6)
Diseases named in the same sentence as GATA6 in open-access papers (continued):
Sharing a sentence is not in itself a finding about the gene and the disease.
breast carcinoma (15 papers, 2017 to 2025). "Interestingly, our eRNA‐TWAS identified multiple known cancer risk genes, such as GATA‐binding factor 6 (GATA6), which is significantly associated with breast cancer (PeRNA‐TWAS = 3.69 × 10−13, PeTWAS = 0.89)." (PMID 39950845, 2025). "As shown in the heatmap of the 20 TFs from the mRNA microarray, FOSL2, SATB1 and GATA6 in CAFs were identified as candidate transcription factors in the progression of angiogenesis in breast cancer." (PMID 33754039, 2021). "In our study, GATA3 and GATA6 transcripts were identified as gene signatures for breast cancer and gastroesophageal cancer, respectively." (PMID 32850691, 2020). "This study aimed to elucidate the molecular mechanisms through which the TET1/SMAD4/GATA6 regulatory axis governs CAF activation in breast cancer, focusing on its role in sustaining TGF-β signaling, promoting stromal-tumor crosstalk, and driving tumor progression." (PMID 40216762, 2025). "GATA6 is reported to be overexpressed in breast cancer, consistent with our pan-cancer analysis." (PMID 30872657, 2019). "Results showed that conditioned media from GATA6/TET1-depleted CAFs reduced migration and invasion of MDA-MB-231 breast cancer cells (p < 0.001 vs. Control 1)." (PMID 40216762, 2025). "In summary, our study elucidates the critical roles of GATA6 and TET1 in sustaining CAF function and driving breast cancer progression." (PMID 40216762, 2025). "To explore this, we analyzed the correlation between GATA6 expression and the TGF-β pathway genes in breast cancer cohorts (TCGA, METABRIC; N = 1,986)." (PMID 40216762, 2025). "Here, we identified the TET1/SMAD4/GATA6 regulatory axis as a central mechanism governing CAF transformation and function in breast cancer." (PMID 40216762, 2025). "Knockdown of GATA6 or TET1 reduced CAF-mediated migration and invasion of breast cancer cells in vitro, while their overexpression enhanced cancer cell aggressiveness." (PMID 40216762, 2025). "To evaluate the role of GATA6 and TET1 in CAF-mediated tumor progression in vivo, we established a xenograft model using CFSE-labeled CAFs co-injected with breast cancer cells into nude mice." (PMID 40216762, 2025). "CLDN6 expression in breast cancer is regulated by transcription factors such as HIF-1a, FoxA2, Gata6, and TTF-1 at the claudin 6 promoter." (PMID 37762277, 2023). "We also found EGFR, MYCN, and MYC in brain cancers;39,40BCL2, MYC, and the loci of IGH translocations in lymph-nodes cancer;41–43CDK12 in breast cancer; CCND1 in liver cancer; and RUNX1, GATA6, and PDE4D in esophageal cancer." (PMID 36163358, 2022). "Additionally, GATA6 is overexpressed in triple-negative breast cancer, where it upregulates slug expression, promoting epithelial-to-mesenchymal transition (EMT) in breast cancer cells." (PMID 40216762, 2025). "Interestingly, in an unrelated breast cancer cell line, MCF7 expression of GATA6 also decreased upon EP300 knockdown." (PMID 35536676, 2022).
cardiac hypertrophy (15 papers, 2013 to 2025). "Forced expression of GATA6 in mouse cardiomyocytes results in an increased cell surface area, while cardiomyocytes specific GATA6 deletion leads to decreased fetal gene expression and reduced cardiac hypertrophy caused by pressure overload stimulation in mice." (PMID 35185581, 2022). "miR-145-5p is an important regulator of cardiac hypertrophy, in contrast, miR-145-5p is a well-established inhibitor of cardiac hypertrophy, suppressing pro-hypertrophic pathways by targeting genes such as GATA6 and IGF1R." (PMID 40874024, 2025). "It inhibits isoproterenol-induced cardiac hypertrophy by targeting transcriptional regulation of the expression and nuclear transport of the transcription factor GATA6." (PMID 40874024, 2025). "Here, we show that fibroblast GATA-4 and GATA-6 promote adaptive remodeling in pressure overload induced cardiac hypertrophy." (PMID 33876316, 2021). "It was revealed that attenuation of myocardial hypertrophy by GA accompany with GATA6 downregulation." (PMID 31921604, 2020). "Interestingly, GATA4 and GATA6 have been reported to contribute to cardiac hypertrophy when overexpressed in cardiomyocytes, interacting with numerous cofactors under complex mechanisms." (PMID 37293953, 2023). "GATA factors play important roles in heart development and cardiac diseases, and overexpression of Gata4 or Gata6 in mouse hearts could lead to cardiac hypertrophy." (PMID 34003819, 2021). "Overexpression of either GATA4 or GATA6 could induce cardiac hypertrophy both in vitro and in vivo." (PMID 34054926, 2021). "Thus, in the adult heart GATA-4 and GATA-6 are each induced in a similar manner during stress-induced hypertrophy, but they do not appear to function together in a synergistic manner in driving cardiac hypertrophy more than either individual transgene." (PMID 24391969, 2013). "The transcriptional code that programs cardiac hypertrophy involves the zinc finger-containing DNA binding factors GATA-4 and GATA-6, both of which are required to mount a hypertrophic response of the adult heart." (PMID 24391969, 2013). "Hybridized mice with knockout of GATA4 or GATA6 and overexpression of the other protein displayed partially reversed cardiac hypertrophy without full heart function recovery." (PMID 35185581, 2022). "The transcription factors GATA4, GATA6 and SP1 are reported to induce cardiac hypertrophy." (PMID 35719043, 2022). "Nevertheless, the cardiomyocyte cross-sectional area similarly increased in Gata4/6fl-Per-Cre and control mice, indicating that the cellular mechanisms enabling compensatory cardiac hypertrophy do not depend on the expression levels of Gata4 and Gata6 in cardiac fibroblasts." (PMID 33876316, 2021). "In addition, GA has regulatory action on cardiac hypertrophy and hypertension through reducing serum levels of CPK, CK-MB, LDH, cTnT, cardiac hypertrophy, infarct size, and down-regulating of p-JNKs, p- ERK, GATA6 and modulating of hemodynamic parameters including LVP, LVEDP, LVSP, LVDP, RPP." (PMID 31921604, 2020). "This indicates that GATA6 is not involved into the cardiac hypertrophy induced by Kindlin-2." (PMID 31767831, 2019). "As the contribution of fibroblasts and vessels is increasingly acknowledged in cardiac hypertrophy, the role of distinct cardiac transcription factors, such as GATA4 or GATA6, needs to be considered also in non-cardiomyocytes." (PMID 34089101, 2021).
lung adenocarcinoma (15 papers, 2015 to 2025). A carcinoma that arises from the lung and is characterized by the presence of malignant glandular epithelial cells. "GATA6 is essential for lineage selection, which directly associates effectors for lung epithelium specification and the inhibition of metastasis in lung adenocarcinoma." (PMID 36101460, 2022). "Reduced GATA6 activity may directly impact metastatic progression of lung adenocarcinoma, while overexpression of GATA6 is associated with poor prognosis in esophageal adenocarcinoma." (PMID 26498761, 2015). "GATA6 plays a context-dependent role in lung adenocarcinoma progression by modulating chromatin accessibility and transcriptional programs, thereby influencing tumor cell proliferation and differentiation based on the cell type and genetic background." (PMID 41155227, 2025). "To delineate the expression pattern of GATA6, we initially conducted an analysis of GATA6 mRNA expression levels in lung adenocarcinoma and normal lung tissues, utilizing data sourced from the TCGA database." (PMID 38483616, 2024). "Our findings unequivocally demonstrated that GATA6 mRNA expression in lung adenocarcinoma tissues was markedly diminished compared to that in normal lung tissues." (PMID 38483616, 2024). "On the other hand, retinoic acid affects the growth of lung adenocarcinoma by inducing cell differentiation and inhibiting proliferation after the activation of GATA6, and the inhibition of Wnt and EGFR." (PMID 36101460, 2022). "SOX21-AS1 predicts prognosis and potentiates proliferation in lung adenocarcinoma, and its silencing represses migration and invasion by regulating GATA6, which decreases the levels of TSPAN8." (PMID 34511042, 2021). "In this study, we uncover a conditional role for the endodermal and pulmonary specifying TF GATA6 in lung adenocarcinoma (LUAD) progression." (PMID 32157212, 2020). "In lung adenocarcinomas, GATA6 and HOPX play critical roles in a lineage-selective pathway to suppress metastasis." (PMID 28146149, 2017). "Moreover, in Hou's dataset 31, the transcription levels of GATA6 in large cell lung carcinoma, lung adenocarcinoma and squamous cell lung carcinoma were significantly downregulated, and their FC are -8.949, -4.042 and -6.186, respectively." (PMID 34093794, 2021). "Moreover, higher expression level of GATA6 in lung adenocarcinoma was significantly correlated with longer survival of patients in all stages." (PMID 32596145, 2020). "GATA6 blocks dedifferentiation and the acquisition of metastatic properties in lung adenocarcinoma cells, but the underlying mechanisms had not been elucidated." (PMID 27325420, 2017). "However, GATA6 may also exert an inhibitory effect on lung adenocarcinoma, indicating varying effects in tumors across cancer types." (PMID 33315534, 2021).
cholangiocarcinoma (12 papers, 2017 to 2025). A carcinoma that arises from the intrahepatic biliary tree (intrahepatic cholangiocarcinoma) or from the junction, or adjacent to the junction, of the right and left hepatic ducts (hilar cholangiocarcinoma). "An example of such a strategy was highlighted for the Gata6 and Muc1/β-Catenin pathway in cholangiocarcinoma." (PMID 37298091, 2023). "It was also found to improve GATA6 expression and be related to a poor prognosis in cholangiocarcinoma." (PMID 34350290, 2021). "Our previous study showed that GATA6 plays important roles in cholangiocarcinoma (CCA) cell invasion and metastasis." (PMID 28270130, 2017). "However, GATA6 also plays a different role in promoting recurrence in cholangiocarcinoma and related to poor prognosis." (PMID 32757451, 2020). "Previously, we found that aberrant expression of GATA6 promoted metastasis in cholangiocarcinoma (CCA)." (PMID 33060563, 2020). "An experimental research has verified that interactions of LOXL2 with GATA6 can induce the expression of VEGFA, which may promote angiogenesis in cholangiocarcinoma subcutaneous tumorsand tumor growth." (PMID 33478536, 2021).
esophageal adenocarcinoma (11 papers, 2008 to 2024). A malignant tumor with glandular differentiation arising predominantly from Barrett mucosa in the lower third of the esophagus. "GATA4 and GATA6 were previously implicated in EAC by the numerous studies that have observed that their loci are frequently amplified in the transition from Barrett's esophagus to cancer." (PMID 30962179, 2019). "During the development of Barrett’s esophagus and the following malignant transformation, the expression of GATA6 is successively increasing resembling its impact on the progression of the disease." (PMID 33300112, 2021). "To further assess the potential role of HNF4A and GATA6 initiating Barrett's esophagus, we examined ATAC-seq signal from normal, Barrett's, and EAC tissue at genomic regions bound by HNF4A alone, GATA6 alone, and regions cobound by GATA6 and HNF4A." (PMID 30962179, 2019). "Interestingly, the expression of GATA-4, GATA-6 and Ihh appear to increase in two precancerous lesions such as Barrett's esophagus and intestinal metaplasias of the stomach." (PMID 18405344, 2008). "For instance, in esophageal adenocarcinoma, SEs that are specific to this type of cancer regulate the overexpression of pro-carcinogenic transcription factors like ELF3, KLF5, GATA6, and EHF." (PMID 38443991, 2024). "A tissue micro array of 192 patients with esophageal adenocarcinoma was analyzed immunohistochemically for DKK2, miRNA-221 expression by RNA scope, and GATA6 amplification by fluorescence in-situ hybridization." (PMID 32075129, 2020). "In support of this, recent single-cell RNA-seq analysis of the esophageal epithelium revealed a population of esophageal submucosal gland cells that are transcriptionally similar to Barrett's esophagus and express HNF4A and GATA6." (PMID 30962179, 2019). "For esophageal adenocarcinoma, it has been shown in a study including 85 EACs that gene amplification of GATA6 affected the patients’ survival in a negative manner." (PMID 33300112, 2021). "Together these data therefore indicate that the regulatory network involving HNF4A, GATA6, HNF1B, and FOXA transcription factors is already established in Barrett's metaplastic, is maintained in EAC cells, and HNF4A may initiate the development of Barrett's esophagus." (PMID 30962179, 2019). "Barrett's esophagus (data not shown) as well as intestinal metaplasia of the stomach were nevertheless highly positive for GATA-4, GATA-6 and Ihh (4A', and 4A")." (PMID 18405344, 2008).
atrial septal defect (10 papers, 2012 to 2026). Interauricular communication is a congenital malformation characterized by a communication between the atrial chambers of the heart. "GATA6 haploinsufficiency is the leading cause of pancreatic agenesis accompanied by congenital heart defects, most commonly Tetralogy of Fallot or atrial septal defects." (PMID 41614934, 2026). "We also generated an iPSC line derived from a CHD patient presenting with an atrial septal defect and congenital diaphragmatic hernia; this patient was found to have a heterozygous frameshift mutation in GATA6 (c.1071delG)." (PMID 40080060, 2025). "Mutations in transcription factor GATA6 have been associated with congenital heart defects, including tetralogy of Fallot, persistent truncus arteriosus, and atrial septal defects." (PMID 22701807, 2012). "At present, CHD associated with GATA6 gene mutations include bicuspid aortic valve (BAV), ventricular septal defect (VSD), patent ductus arteriosus (PDA), atrial septal defect (ASD), persistent truncus arteriosus (PTA), and tetralogy of Fallot (TOF)." (PMID 31781165, 2019). "It was previously found that Wnt2 and Gata6 act in the same genetic pathway in the posterior SHF during heart development and when inactivated cause atrial septal defects among other anomalies." (PMID 28346476, 2017). "Because GATA6 is critical for cardiac outflow tract formation, the clinical presentation is dominated by a triad of Neonatal Diabetes, Pancreatic Exocrine Insufficiency, and Congenital Heart Defects (most commonly Tetralogy of Fallot or atrial septal defects)." (PMID 41614934, 2026).
hepatocellular carcinoma (9 papers, 2015 to 2026). A malignant tumor that arises from hepatocytes. "Upregulation of miR‐181 in hepatocellular carcinoma cancer stem cells with aggressive features led to the downregulation of GATA6, which is implicated in hepatocellular differentiation." (PMID 41152570, 2026). "Actually, GATA6 has been reported to direct hepatocellular carcinoma cells to glycolytic metabolism and fosters tumorigenicity, self-renewal and metastasis by transcriptional regulation of PKM2 expression." (PMID 33390837, 2021). "Microarray and real‐time PCR analyses in hepatocellular carcinoma cell lines indicated a correlation between BCL11B and GATA6, a gene reported to be correlated with oncogenic activities and resistance to anthracycline, which is often used for hepatocellular carcinoma chemotherapy." (PMID 37293953, 2023). "Our results indicated that overexpression of BCL11B amplifies GATA6 expression in hepatocellular carcinoma in vitro and in vivo that leads to anti‐apoptotic signal activation, and induces resistance to chemotherapy, which influenced the postoperative prognosis." (PMID 37293953, 2023). "In addition, miR-363 is known to target many genes in addition to GATA6, including S1PR1, which is crucial for the growth of hepatocellular carcinoma cells." (PMID 26387746, 2015). "Moreover, compared with non-tumoral liver tissues, GATA6 expression is also reduced in hepatocellular carcinoma tissues, and it was considered to be a potential prognostic biomarker and therapeutic target for liver cancer." (PMID 33013201, 2020).
ventricular septal defect (9 papers, 2014 to 2026). The presence of a defect (opening) in the septum that separates the two ventricles of the heart. "The most common other extrapancreatic features were heart (89.8%, mainly ventricular septal defect) and hepatobiliary (mainly gallbladder agenesis) in 59 GATA6 mutation carriers." (PMID 37204622, 2024). "GATA transcription factor 6 (GATA6) gene promoter DNA sequence variants (DSVs) in ventricular septal defect (VSD) patients and controls." (PMID 25036032, 2014). "In the present study, GATA6 gene promoter was genetically and functionally analyzed in large groups of patients with ventricular septal defect (VSD) (n = 359) and ethnic-matched healthy controls (n = 365)." (PMID 25036032, 2014). "Congenital heart defects (atrial and ventricular septal defects, the tetralogy of Fallot, tricuspid valve atresia, pulmonary artery stenosis, and the transposition of the great arteries) are described in up to 93% of patients with GATA6 syndrome." (PMID 39596087, 2024). "Knockout mice for Tbx1 or double heterozygous knockout mice for Gata4 and Gata6 exhibit fetal nuchal edema with ventricular septal defect (VSD) and persistent truncus arteriosus (PTA)." (PMID 36111337, 2022). "GATA6 gene mutations have been reported in familial and isolated CHD patients in different ethnic populations, including atrial septal defect, atrioventricular septal defect, persistent truncus arteriosus, tetralogy of Fallot and ventricular septal defect (VSD)." (PMID 25036032, 2014). "Heterozygous Gata6 loss-of-function mutations alone or humanized Mib1 mutations in a NOTCH1-sensitized genetic background cause bicuspid aortic valve (BAV) and a membranous ventricular septal defect (VSD), consistent with MIB1 and NOTCH1 functioning in the same pathway." (PMID 39057643, 2024).
myocardial infarction (8 papers, 2019 to 2025). Gross necrosis of the myocardium, as a result of interruption of the blood supply to the area, as in coronary thrombosis. "Interestingly, GATA6-positive macrophages that invade the epicardium from the pericardial space following experimental myocardial infarction were antifibrotic, despite a rapid loss of GATA6 expression." (PMID 33536334, 2021). "Recent studies demonstrated that in the mouse model of myocardial infarction, Gata6+ pericardial cavity macrophages also quickly invade the epicardium where they lost Gata6 expression." (PMID 40963611, 2025). "It is worth contemplating whether Gata6+ pericardial cavity macrophages (GPCMs) have a similar effect, migrating to damaged myocardial sites and facilitating tissue repair after myocardial infarction." (PMID 39087342, 2024). "Additionally, Deniset et al17 recently reported that the PF contains a subpopulation of antifibrotic proregenerative GATA binding protein-6 (GATA-6) + Mφ, able to migrate into the myocardium in response to myocardial infarction (MI) induced by coronary ligation in mice." (PMID 39444932, 2024). "When these macrophages invade the injured heart muscle, the expression of Gata6 (GATA binding protein 6) is lost, but Gata6 can continue to function in repair after myocardial infarction." (PMID 39087342, 2024). "Furthermore, the involvement of Gata6 + pericardial macrophages (GPCMs) in the progression of cardiac fibrosis subsequent to myocardial infarction (MI) was observed." (PMID 37817547, 2023). "After myocardial infarction, GATA binding protein 6 (GATA6) + macrophages in the pericardial cavity are recruited to the remote infarct area to function in a cardioprotective role." (PMID 34760943, 2021).